STAT3 (signal transducer and activator of transcription 3)
Diseases named in the same sentence as STAT3 in open-access papers (continued):
Sharing a sentence is not in itself a finding about the gene and the disease.
cancer (continued). "Therefore, we wondered if STAT3 acts in synergy with Ras activation to sustain the TW1 expression in CR neutrophils since the aberrant Ras activation can sustain cell activities, such as cancer cell proliferation." (PMID 34335965, 2021). "STAT3 may be a safe target for cancer therapeutics as STAT3 deletion does not affect the viability of differentiated cells, but proficiently blocks the cell proliferation." (PMID 34535145, 2021). "Moreover, another study has proposed the anti-cancer potential of PL might be attributed to its ability to inhibit the JAK1,2/STAT3 signaling pathway." (PMID 36046754, 2021). "Therefore, blockade of CXCR4/STAT3 pathway could be a promising approach for the efficient sensitizing NSCLC cells to IR, hence being useful for the radiotherapy of this devastating cancer." (PMID 33414415, 2021). "Therefore, the CIB-6-induced inhibition of STAT3 and increase in E3 ligase β-TrCP expression may be beneficial to enhance the IFN-induced anti-cancer effects in immunotherapy." (PMID 33805945, 2021). "Furthermore, targeting one of the upstream effectors of STAT3 is unlikely to be sufficient for cancer therapy, because multiple upstream activators converge on the STAT3 signaling." (PMID 33753770, 2021). "Therefore, it would not be surprising if STAT3 plays a role in promoting fibrosis in cancer, however, this warrants further investigation." (PMID 34858425, 2021). "Interestingly, the ectopic expression of STAT3 in HEK293T did not significantly increase XRCC1 protein content (1.03 ± 0.035), indicating that STAT3 has a less significant role in regulating XRCC1 expression in HEK293T and occurs through a cancer-related, possibly TNBC-specific, mechanism." (PMID 34067421, 2021). "Anxa2 has been proven facilitating cancer progression via multiple aspects by interacting with other biomolecules, among which the Anxa2 rearrangement gene expression in cancer cells through oncogenic transcription factor like NF-κB, YAP1 in Hippo pathway and STAT3/6." (PMID 34502195, 2021). "In contrast, ILK may regulate STAT3 indirectly via its dependent pathway, PI3K/Akt, in cancer." (PMID 34163519, 2021). "ANXA1 also promotes the proliferation and metastasis of cancer cells through the binding of EphA2, the suppression of autophagy and the activation of the PI3K/AKT pathway and promotes proliferation and migration via the regulation of the IL-6/JAK2/STAT3 pathway." (PMID 34439260, 2021). "Regrettably, thus far, no STAT3 inhibitor has been approved for cancer therapy." (PMID 33259114, 2021). "Granulocyte-colony stimulating factor (GCSF) may gain a high level by the stimulation of cancer cells, which activate the signaling pathway of Janus Kinase (JAK)-signal transducer and activator of transcription 3(STAT3), contributing to the migration and proliferation of neutrophil." (PMID 34746222, 2021). "The findings suggested that curcumin induced the inhibition of STAT3 phosphorylation and therefore inhibited its translocation into the nucleus, which resulted in a slightly reduced NFĸB-STAT3 protein interaction and downregulation of CD44 as the marker of cancer stem cell phenotype." (PMID 34298639, 2021). "Infection of H. pylori also causes the activation of signal transducer and activator of transcription 3 (STAT3), resulting in the overexpression of anti-apoptotic and pro-proliferative proteins such as Bcl-xL, MCL-1, c-myc, and cyclin D1, which may promote cancer progression." (PMID 34948234, 2021). "Indeed, seletalisib totally inhibited IL-22-induced STAT3 phosphorylation in Tyr705 at 30 min and 1 h of stimulation, thus suggesting a possible molecular link between PI3Kδ and STAT3 in human keratinocytes, as previously demonstrated in PI3K-transformed cancer cells." (PMID 34685616, 2021).
cancer (continued). "Signal transducer and activator of transcription 3 (STAT3)/Cyclin-dependent kinases are multifunctional proteins that play an important implicative role in cancer initiations, progression, drug resistance, and metastasis, and has been extensively explored in cancer therapy." (PMID 33668805, 2021). "The α6β4 integrin mediates activation of Src and STAT3 to suppress expression of ACSL4, an enzyme that enriches membranes with long polyunsaturated fatty acids and is required for ferroptosis to protect adherent epithelial and carcinoma cells from ferroptosis induced by erastin." (PMID 34717678, 2021). "Pin1 is highly expressed in a majority of cancers, and elevation in Pin1 levels by either OSM or IL-6 involves the activation of both STAT3 and NF-κB through direct binding with the pSer/Thr-Pro motifs of STAT3 and p65 in the nucleus that results in promotion of STAT3 transcriptional activation." (PMID 31952344, 2020). "Interestingly, the inhibition of STAT3 by β-caryophyllene produced nontoxic effects in normal cholangiocytes, thus suggesting the involvement of specific mechanisms for cancer cells." (PMID 32252311, 2020). "We further identified that STAT3 functions to promote the transcription of the activating transcription factor 6 (ATF6), which induces endoplasmic reticulum stress to promote cellular autophagy, granting cancer cell resistance to both cisplatin and paclitaxel treatment." (PMID 32080166, 2020). "Until now, numerous STAT3 inhibitors have been discovered and characterized, however; none of them has been approved by FDA for clinical use in the treatment of cancer 8,13, suggesting that mere inhibition of STAT3 is not sufficient enough to effectively eradicate cancer cells." (PMID 32328177, 2020). "However, in cancer cells such as ACHN cells, in which eIF4B plays an important role, it is possible to stimulate cell growth by regulating cap‐dependent translation through the expression of eIF4B and mLST8 by STAT3." (PMID 32495998, 2020). "Whilst we demonstrated that E6-mediated STAT3 phosphorylation required IL-6 autocrine/paracrine signalling, we do not know how E5 and E7 induce STAT3 phosphorylation, and whether or not this contributes to cancer development." (PMID 32899142, 2020). "We could hypothesize that inflammatory responses observed in the middle and inner ear of our knockout mice could be due to enhanced expression of STAT3/STAT5 in absence of STAT1 as observed in cancer cells." (PMID 32991625, 2020). "Last but not least, the optimization of combination therapies using STAT3/5 inhibitors with molecules targeting tyrosine kinases or other key players in cancer will be required for finding the right combination that safely unlocks drug resistance in hematologic cancers." (PMID 31963765, 2020). "Importantly, elevated expression of activated STAT3 serves as a marker of negative prognosis in many types of cancers." (PMID 32967366, 2020). "We have demonstrated that STAT3 acts as a trans‐acting factor for MLST8 gene expression and the protein level of mLST8, a core component of mechanistic target of rapamycin complex 1 and 2, positively regulates cap‐dependent translation through 4E‐BP1 phosphorylation in cancer cells." (PMID 32495998, 2020). "Notably, pterostilbene exhibited a greater inhibitory effect against HeLa cancer stem-like cells than resveratrol through more potent inhibition of the expression levels of stemness markers, such as CD133, Oct4, Sox2, and Nanog, as well as STAT3 signaling." (PMID 31935877, 2020). "Similarly, we observed in vitro that both the myostatin administration and the cancer cell coculture stimulated inflammatory pathways in C2C12 myoblasts and myotubes by increasing the phosphorylation of STAT3 and C/EBPβ, markers of increased inflammatory response." (PMID 32365803, 2020). "Tetrac did not affect status of total STAT3 or phosphorylated STAT3 in both cancer cell lines." (PMID 32630719, 2020).
cancer (continued). "As available clinical and nonclinical data from cancer studies have reported, overexpression of STAT3 has a crucial role in maintaining cancer hallmarks, therefore, in the current study, we explored the status of activated STAT3." (PMID 32182833, 2020). "However, the effects of MGN on mitochondrial complex I activity, ROS formation, AMPK activation, and STAT3 phosphorylation in precancerous or cancer cells are not known." (PMID 32264893, 2020). "ROS are highly expressed in LECs during the onset of diabetic cataracts stimulated by high glucose, and could induce EMT by activating several transcription factors, such as Snail, STAT3, and ZEB1, which can be activated by the Notch, G-CSF, MAPK, and PI3K/Akt signaling pathways in cancer cells." (PMID 33274006, 2020). "The alternative STAT3 modifications (non-canonical STAT3 activation) are acetylation at Lys685 or phosphorylation at Ser727, which were reported to play an important role in cancer progression." (PMID 33327495, 2020). "Indeed, in cancer conditions RAGE chronically activated by its ligands induces the activation of multiple catabolic pathways, that is, p38 MAPK and STAT3, and the deactivation of the anabolic kinase, Akt, leading at the same time to hampered MyHC synthesis and increased muscle protein degradation." (PMID 32159297, 2020). "The correlation analysis of hnRNPs with cancer‐related pathways suggested that hnRNPs significantly contributed to the activation or suppression of various oncogenic pathways including protein secretion, mitotic spindle, G2/M checkpoint, DNA repair, IL6/JAK/STAT3 signal and coagulation." (PMID 32915499, 2020). "Interleukin-6 (IL-6) has been proven to be a significant nonmatrix target of MMPs in cancer growth and development by modulating many signaling molecules, in particular signal transducer and activator of transcription-3 (STAT-3) and extracellular signal-regulated kinase (ERK) 1/2." (PMID 33014057, 2020). "Mitochondrial STAT3 activation has not been characterized in mitochondria from cancer cells." (PMID 31600993, 2019). "However, STAT3 can trigger autophagy also without phosphorylation usually detected in cancer, in line with our observations." (PMID 32565533, 2019). "Interestingly, constitutively Ser727-phosphorylated STAT3 is present in many human cancers and is sufficient to drive tumorigenesis independent of Tyr705 phosphorylation in various models." (PMID 31143708, 2019). "Published studies have suggested that STAT3, a TF activated in response to various cytokines and growth factors, in TC may function as onco-suppressor rather than as cancer promoting factor." (PMID 31200515, 2019). "In addition, in CSE-treated HBE cells, interleukin (IL)-6 activated phosphorylated signal transducer and activator of transcription 3 (STAT3) and increased the levels of HOTAIR, which has been found to be involved in the formation of cancer stem cells and malignant transformation." (PMID 31711545, 2019). "Signaling pathways such as PI3K/Akt, Stat3, NF-κB and HIF-1 play key roles in expression of PD-L1, butyrate has been shown to inhibit these signaling pathways, which may result in decreased PD-L1 expression and increased anti-cancer immune responses." (PMID 31067776, 2019). "While numerous preclinical studies on cell lines and animal models justify further development, the use of direct STAT3 inhibitors in clinical trials for cancer therapy is limited by lack of cell penetrance, rapid degradation, lack of specific binding, and concerns for unpredicted toxicities." (PMID 31684088, 2019). "This suggests that the anticancer effect of PTC-209 on cancers cells involves, although maybe not solely, the inactivation of the STAT3 signaling Pathway." (PMID 31695609, 2019).
cancer (continued). "It is conceivable to hypothesize that, in pathological or cancer staging events when these stress conditions are not completely established (lower concentration of ROS and/or not hypoxia conditions), the STAT3/HIF-1α/PKM2 axis may not be yet active." (PMID 31500219, 2019). "To date, attempts have been made to target stemness markers, such as STAT3 and NANOG, as well as pathways that regulate malignant stemness, most notably the Wnt/β-catenin, Notch, hedgehog, and JAK-STAT pathways, which promote stemness features in various cancers." (PMID 31137841, 2019). "In addition, considering that STAT3 is persistently activated in many human cancer tissues and cell lines, if FOXL2 is clearly regulated by STAT3, the question remains of whether the new STAT3-FOXL2 signaling pathway functions cancer progression." (PMID 31221094, 2019). "Hence, an inflammatory signal from non-transformed, spontaneous, immortalized cells to cancer cells initiates a positive feedback loop involving IL-6/NF-κB/Lin28/let-7 miRNA and STAT3 activation." (PMID 31557902, 2019). "By literature mining we identified some interesting genes (as STAT3, HIF1a, NFKB1, KRAS) that have been reported to play an important role in biological processes as inflammation, EMT, coagulation and angiogenesis, which are at the basis for cancer and cardiovascular diseases." (PMID 29703138, 2018). "While its specific role in the pathology of cancer cachexia has not been elucidated yet, it is known that STAT3 promotes expansion of the satellite cells pool in vivo and in vitro, and may play a negative role in promoting differentiation and muscle repair." (PMID 30072615, 2018). "Moreover, in obese patients, the cytokines produced by adipocytes and immune cells could promote the survival of cancer stem cells (CSCs) through the activation of the Notch3 and IL-6/JAK2/STAT3 pathways, as demonstrated in other cancer models." (PMID 30366466, 2018). "However, in the vast majority of cancers, macrophages exhibit an immunosuppressive endotype characterized by low levels of inflammatory molecules (IL18, IL12, and TNFα), and an increased expression of transcripts expressed by AAMs (Il10, Stat3, and ll13)." (PMID 29594035, 2018). "There is a great deal of overlap between CCND2, G1/S-specific cyclin D2, and STAT3, including the prolactin and FOXO signaling pathways, which are inactivated by major oncogenic signals such as the PI3K and MAPK pathways, and their expression is also repressed by microRNAs in multiple cancer types." (PMID 29992138, 2018). "However, disruption of either NF-κB or STAT3 signaling does not lead to cell death, therefore their inhibitors should be combined with cancer-specific cytotoxic drugs." (PMID 29932172, 2018). "Moreover, STAT3 is found to be active in many human cancers, and crucially involved in induction of BIRC5/survivin expression, and has been observed to correlate with increased invasion, metastasis and chemo-resistance in cancer." (PMID 30481203, 2018). "Using cancer-related pathway probes, we showed that STAT3 inhibited the expression of several IFN response genes in GICs, such as the chemokines CXCL9, CXCL10 and CXCL11, which is consistent with the finding that STAT3 can inhibit the expression of IFN response genes." (PMID 29774125, 2018). "Although acid alone may up‐regulate selected “oncomirs”, it was not capable of accelerating activation of oncogenic STAT3 or other cancer‐related molecular events." (PMID 29516639, 2018). "Also, similar to STAT3, STAT5 is also overactive in many invasive human cancers." (PMID 30109213, 2018). "Hence, the present study aimed to test the hypothesis that targeting of STAT3 enables cancer suppression at multiple levels via attenuation of the oncogenic potential of PLOD3 owing to upstream and downstream aberrations in cancer metastasis pathways." (PMID 30442941, 2018).
cancer (continued). "Moreover, we provide evidence that this may be associated with changes in mitochondrial function, including modulation of STAT3 and prohibitin expression, and that CBD can be used to sensitize cancer cells to chemotherapy." (PMID 30150937, 2018). "The JAK2/STAT3 pathway has been shown to mediate resistance to tamoxifen in CD44+CD24−/low BCSC, and that the IL6/JAK1/STAT3/Oct4 pathway may be involved in the conversion of breast non-cancer stem cells to BCSC." (PMID 30018256, 2018). "What we could suggest from cancer cell migration studies is that in the presence of the BDNF, p75NTR may be activated by TrkB and Kidins220 upon ephrin receptor phosphorylation leading to STAT3 activation and RhoA inhibition." (PMID 30190671, 2018). "Together with growing evidence from preclinical and clinical studies, our observations highlight potential of targeting STAT3 and/or PD-L1 to improve CMT efficacy in HNSCC patients possibly by neutralizing this checkpoint molecule on immunosuppressive myeloid cells as well as cancer cells." (PMID 29541413, 2018). "The ability of EGCG to restore the levels of p-STAT3 and Bcl-xL in the cochlear cells, but not in cancer cells, could account for its protection of the cochlea without compromising cisplatin’s chemotherapeutic efficacy." (PMID 28703809, 2017). "Such an increase was also evident for STAT3 phosphorylation in resistant cells and clones; on this regard, the proteins belonging to the STAT family of transcription factors, they are activated by cytokines and growth factors receptors and led to cancer progression." (PMID 29113311, 2017). "In conclusion, we found that BMSCs may activatethe IL-6/STAT3 signaling pathway and promote cell invasion in Bel-7404cells, suggesting that this protumor effect should be seriously consideredbefore clinical application of MSC-mediated cancer therapy." (PMID 28659496, 2017). "However, cancer genes, including CDK5 and STAT3, represent the most influential factors." (PMID 29312535, 2017). "Our finding of the TRIM8‐STAT3 positive feedback loop in GBM provides new insight into the regulation of STAT3 and offers other opportunities for the development of treatments that impair stemness in GSC and potentially in other cancers that show TRIM8 overactivity." (PMID 28100038, 2017). "STAT3 staining intensities in all samples (initial negative biopsies, cancer positive cores, and other negative cores from the same batch biopsies) of cancer patients was significantly higher than that of benign patients (p<0.001), with a high sensitivity (80.8%) and specificity (76.3%)." (PMID 29156772, 2017). "The effect of Nur77 on STAT3 has not been reported in either cancer cells or ECs." (PMID 28978186, 2017). "In contrast to normal cells where activation of STAT3 is only transient due to a host of endogenous protein regulators (e.g., PIAS, SOCS), aberrant and constitutive activation of STAT3 has been detected in a wide variety of human cancers, including solid tumors as well as blood malignancies." (PMID 26883202, 2016). "Similarly, inhibiting STAT3-mediated signaling with a small molecule inhibitor (BBI608) resulted in suppressed stemness-related genes including Nanog, Sox2 and OCT4 which are often upregulated following conventional cancer therapy." (PMID 26742077, 2016). "Our findings suggested that aspirin could suppress cancer cell growth and metastasis through the induction of lncRNA OLA1P2 transcription and the subsequent blocking of phosphorylated STAT3 (signal transducer and activator of transcription 3) homodimers formation." (PMID 26898989, 2016). "Although, polyphenols from blueberry have demonstrated inhibitory activities on cancer cells via the control of inflammatory cytokines such as IL-6, dramatic and biphasic increase of IL-6 occurs early in CSC cellular transformation, independently of STAT3 decrease." (PMID 26762586, 2016).